SUCLA2 (succinate-CoA ligase ADP-forming subunit beta)
Diseases named in the same sentence as SUCLA2 in open-access papers:
SUCLA2 is named in the same sentence as 44 diseases in open-access papers, as found by Europe PMC text mining. Sharing a sentence is not in itself a finding about the gene and the disease. The quoted sentences say what the papers report.
mitochondrial DNA depletion syndrome (9 papers, 2014 to 2024). The mitochondrial DNA (mtDNA) depletion syndrome (MDS) is a clinically heterogeneous group of mitochondrial disorders characterized by a reduction of the mtDNA copy number in affected tissues without mutations or rearrangements in the mtDNA. "SUCLA2‐deficient mitochondrial myopathy has been traditionally considered a mitochondrial DNA depletion syndrome (MDS)." (PMID 39482887, 2024). "Two patients had only one MMAA variant each, and one patient had mild MMA due to mitochondrial DNA depletion syndrome caused by a SUCLA2 variant." (PMID 38750596, 2024). "We identified one case of mitochondrial DNA depletion syndrome with mild isolated MMA due to a homozygous c.851G > A variant in the SUCLA2 gene, which is a rare condition with only 41 mutation types reported to date." (PMID 38750596, 2024). "Therefore, variants in SUCLA2 can lead to mitochondrial DNA depletion syndrome with encephalomyopathic features and mild isolated MMA." (PMID 38750596, 2024). "Variants in the genes SUCLG1 and SUCLA2 cause mitochondrial DNA depletion syndrome, which may be associated with mild isolated MMA, a distinct type of isolated MMA." (PMID 38750596, 2024). "Recessive SUCLA2 mutation causes mtDNA depletion syndrome, which could cause mild methylmalonic aciduria, recurrent vomiting, hypotonia, dehydration, respiratory distress, neonatal encephalopathy, and progressive lethargy." (PMID 35235001, 2022). "A subsequent literature review of the genes containing these variants identified SUCLA2 as the probable causative disease gene, since it had previously been identified as a cause of mitochondrial DNA depletion syndrome‐5, with which the patients had been diagnosed." (PMID 26037133, 2015).
prostate carcinoma (5 papers, 2016 to 2023). A carcinoma that arises from epithelial cells of the prostate gland. "Surprisingly, particularly in prostate cancers, SUCLA2 gene deletion was found to take place upon RB1 loss with near to 100% prevalence." (PMID 34359636, 2021). "SUCLA2 has been previously shown to be significantly downregulated in prostate cancer." (PMID 37601653, 2023). "Indeed, depletion of SUCLA2 in prostate cancer cells resulted in lower mitochondrial/respiratory activity and enhanced glycolysis." (PMID 34359636, 2021). "Interestingly, the Aurora A inhibitor that targets RB1 loss in a synthetic lethal manner synergized with thymoquinone in prostate cancer cells doubly deficient of RB1 and SUCLA2." (PMID 34359636, 2021). "Our model also predicts that GTP-specific beta subunit of succinyl-CoA synthetase (SUCLG2) is selectively lethal in malignant prostate cancer cells because the alternative route via ATP-specific succinyl-CoA synthetase (SUCLA2) is absent in the malignant model." (PMID 32103057, 2020).
Methylmalonic aciduria (3 papers, 2016 to 2024). Increased concentration of methylmalonic acid in the urine. "SUCLG1-related MDDS 9 (encephalomyopathic type with methylmalonic aciduria, OMIM #245400) and SUCLA2-related MDDS 5 (encephalomyopathic type with or without methylmalonic aciduria, OMIM #612073) are rare subtypes of MDDS caused by biallelic pathogenic variations in the SUCLG1 and SUCLA2 genes." (PMID 38073635, 2023).
mitochondrial encephalomyopathy (3 papers, 2008 to 2014). A heterogenous group of disorders characterized by alterations of mitochondrial metabolism that result in muscle and nervous system dysfunction. "Caspase-3 activation leads to DNA fragmentation so we performed the TUNEL assay in muscle biopsies from patients with TK2 mutations (P3, P4), a patient with SUCLA2 mutations (P10) and patients with confirmed mitochondrial encephalomyopathy (P6, P7 and P12)." (PMID 24484525, 2014). "Mutations in SUCLA2 were first identified as a cause of severe mitochondrial encephalomyopathy with skeletal muscle mtDNA depletion through homozygosity mapping of a consanguineous family with multiple affected members." (PMID 24271779, 2014). "Subsequently, it was demonstrated that SUCLA2-associated mitochondrial encephalomyopathy with mtDNA depletion is quite common in the Faroe Island population, with an incidence of 1 in 1700 secondary to a founder mutation in SUCLA2." (PMID 24271779, 2014). "Mutations in SUCLA2 have previously been associated with mitochondrial encephalomyopathy, a disorder which causes fatigue and muscle weakness." (PMID 18986552, 2008).
deafness (2 papers, 2016 to 2019). An inherited or acquired condition characterized by the complete loss of the ability to hear from one or both ears. "In patients with severe hypotonia, deafness, and Leigh-like syndrome, mutations have been found in SUCLA2, which is associated with mtDNA depletion." (PMID 27428959, 2016). "Mutations in the SUCLA2 gene encoding ADP-forming succinyl-CoA synthase usually cause severe infantile encephalomyopathies but they may present in childhood with psychomotor delay, deafness, myopathy, ataxia, and chorea." (PMID 31718067, 2019).
encephalomyopathies (2 papers, 2019 to 2024). "Pathogenic variants in SUCLA2 have been associated with mitochondrial DNA depletion syndrome, type 5 (MTDPS-5, OMIM ID: 612073)." (PMID 39070054, 2024). "In this case, we present a Chinese family exhibiting a rare and severe early progressive encephalomyopathy, diagnosed with mitochondrial DNA depletion syndrome, type 5 (MTDPS-5), and carrying compound heterozygous variants (c.1234C>T; g.48569263–48571020del1758insATGA) in the SUCLA2 gene." (PMID 39070054, 2024).
hepatocellular carcinoma (2 papers, 2015 to 2025). A malignant tumor that arises from hepatocytes. "Since then other reports also support a role for MPV17 and deoxyguanosine kinase SUCLA2 mutation induced hepatocellular carcinoma in MDS patients." (PMID 26468652, 2015).
Mitochondrial encephalopathy (2 papers, 2014 to 2021). "The identification of an ES cell clone with a gene trap of Sucla2 validates the screening strategy given that SUCLA2 is a known mitochondrial disease gene that causes mitochondrial encephalopathy with mtDNA depletion." (PMID 24271779, 2014). "Mutation in TRNT1 and SUCLA2 has been implicated in patients with mitochondrial encephalopathy." (PMID 33484326, 2021).
pancreatic ductal adenocarcinoma (2 papers, 2022). An infiltrating adenocarcinoma that arises from the epithelial cells of the pancreas. "A recent study reported that GLS1 is overexpressed in human pancreatic ductal adenocarcinoma (PDAC) and SUCLA2 mediated succinylation of GLS (K311) could eliminate oxidative stress." (PMID 35366902, 2022).
cardiac hypertrophy (1 paper, 2020). "Fatty acid oxidation (Acadm, Etfdh, Acadl, Acadvl, Eci1, Hadh, Phyh, Acaa2, Hadha, Hadhb, Cd36), glucose metabolism (Dld, Pdha1, Pgam1, Pgam2, Acss1, Ldhb, Fh1, Slc2a4, Aldh6a1), TCA cycle (Aco2, Dld, Fh1, Ogdh, Sucla2, Sdha, Idh3b, Idh2) were up-regulated by hispidulin in cardiac hypertrophy." (PMID 33324687, 2020).
cognitive decline (1 paper, 2023). "Pearson correlation analysis found that the IDH3G, DLD, SUCLA2, MDH1 showed moderate positive correlations with MMSE scores (r = 0.365–0.441, p < 0.05), suggesting that their expression can effectively track the progression of cognitive decline." (PMID 37575300, 2023).
Cognitive impairment (1 paper, 2023). Abnormal cognition is characterized by deficits in thinking, reasoning, or remembering. "Here, we found that SUCLA2 was significantly decreased in AD brain and blood cells, and correlated with Aβ, Tau and MMSE scores, suggesting that SUCLA2 may be closely related to the pathological development and cognitive impairment of AD, and it may be a potential diagnostic and therapeutic target." (PMID 37575300, 2023).
Encephalopathy (1 paper, 2023). Encephalopathy is a term that means brain disease, damage, or malfunction. "Epilepsy has also been described, more commonly in association with SUCLA2 than SUCLG1 gene mutations; however, none of the patients in this series developed epileptic seizures or evident encephalopathy." (PMID 38073635, 2023).
Infantile encephalopathy (1 paper, 2020). Encephalopathy with onset in the infantile period. "For instance, PGK, NNT, SUCLA2, and FH have been linked to inherited disorders including, but not limited to, infantile encephalopathy, X-linked inherited disorders, myopathies, and neural tube defects." (PMID 33425810, 2020).
ischemia (1 paper, 2022). A hypoperfusion of the BLOOD through an organ or tissue caused by a PATHOLOGIC CONSTRICTION or obstruction of its BLOOD VESSELS, or an absence of BLOOD CIRCULATION. "Only a few changes in the mitochondrial proteome were found following ischemia; these were the down-regulation of the TCA cycle enzymes DLD and SUCLA2 and the ETC members MT-ND2 and ATP5A1." (PMID 35216205, 2022). "This is the case of SUCLA2 and DLD, which were down-regulated during ischemia and not recovered after revascularization, and the isocitrate dehydrogenase components IDH3A and IDH2, which were found to be down-regulated after the re-establishment of coronary blood flow." (PMID 35216205, 2022).
lactic acidosis (1 paper, 2023). Metabolic acidosis characterized by the accumulation of lactate in the body. "In the present case series, we describe patients with MDDS secondary to pathogenic variants in the SUCLG1 and SUCLA2 genes who had mitochondrial encephalopathy, lactic acidosis, and elevated MMA in urine." (PMID 38073635, 2023). "Thus, the presence of MMA in succinyl–coenzyme A synthase deficiency represents a highly sensitive screening test for MDDS related to SUCLA2 and SULG1 gene mutations in patients presenting with non-specific and variable neurological presentation and lactic acidosis." (PMID 38073635, 2023).
methylmalonic acidemia (1 paper, 2023). A genetically heterogenous inherited disorder characterized by abnormalities in the metabolism of lipids and proteins. "In a Chinese study of 310 isolated methylmalonic acidemia patients, approximately 3.2% of patients were found to harbor a mutation in SUCLG1, while only 0.9% of them were secondary to the SUCLA2 mutation." (PMID 38073635, 2023).
Mitochondrial myopathy (1 paper, 2024). "SUCLA2 loss within murine skeletal muscle yields a model of SCS‐deficient mitochondrial myopathy with reduced body weight, muscle weakness and exercise intolerance." (PMID 39482887, 2024). "Here, by restricting Sucla2 mutagenesis to the murine skeletal muscle via the Cre/loxP system, the development of a viable model of SUCLA2‐deficient mitochondrial myopathy has been achieved." (PMID 39482887, 2024).
Obesity (1 paper, 2026). Accumulation of substantial excess body fat. "In an obesity-related study, AMPK phosphorylates the SUCLA2 metabolic enzyme to restrict glutaminolysis, thereby reducing succinate accumulation and blocking NLRP3 inflammasome activation, which ultimately attenuates pro-IL-1β transcription." (PMID 41508030, 2026).
renal carcinoma (1 paper, 2021). A carcinoma arising from the epithelium of the renal parenchyma or the renal pelvis. "The high expression of GPI, FBP1, ALDOB, and SUCLA2 indicated longer OS and a low risk of developing renal cancer." (PMID 33564363, 2021). "The high expression of FBP1, ALDOB, LDHD, and SUCLA2 indicated a longer DFS and a low risk of developing renal cancer." (PMID 33564363, 2021).
retinal detachment (1 paper, 2022). An eye emergency condition which may lead to blindness if left untreated. "The COX IV and SUCLA2 findings suggest that there is a generalised loss of inner segment mitochondrial proteins after retinal detachment." (PMID 36467607, 2022). "We examined the effect of retinal detachment upon expression of SUCLA2, the ATP-forming β-subunit of SUCL." (PMID 36467607, 2022).
varicocele (1 paper, 2020). A condition characterized by the dilated tortuous veins of the spermatic cord with a marked left-sided predominance. "Nonetheless, proteins, such as CLGN, FTH1, MDH1, MIF, PPP3CA, SUCLA2, and PSMA7, involved in sperm function, apoptosis, and oxidative stress were present in a low and very low abundance in the unilateral and bilateral varicocele group, respectively." (PMID 32365753, 2020).
tumor (11 papers, 2018 to 2024). "Importantly, succinylation of tumor-highly expressed GLS and glutaminolysis in PDAC are governed by dynamical association of GLS with SUCLA2, which confers tumor cells greater capacity to counteract oxidative stress and support tumor growth." (PMID 34913133, 2022). "Additionally, the discovery of biomarkers that help quick diagnosis of SUCLA2 deficiency in tumor tissue would be forthcoming." (PMID 34359636, 2021). "Consistently, mouse studies showed that expression of SUCLA2 S79A or GLS K311R significant inhibited tumor growth and reduced the levels of GSH/GSSG ratios in tumor tissues." (PMID 34913133, 2022). "This effort discovered succinyl lyase A2 (SUCLA2) gene that locates around 302 kb away from RB1 tumor suppressor gene in human chromosome 13q14.2." (PMID 34359636, 2021). "Under oxidative stress, SUCLA2 increases glutamine catabolism and the production of nicotinamide adenine dinucleotide phosphate as well as glutathione by activating GLS, thereby ameliorating oxidative stress and promoting tumor growth." (PMID 38062233, 2023). "For example, SUCLA2 mediated GLS succinylation and promoted tumor cell progression." (PMID 37582794, 2023). "Moreover, some other non-structural nuclear MTRGs, such as SUCLA2, DARS2, and TRMU, can regulate tumor cells and influence the prognosis of cancer patients." (PMID 34692528, 2021).
cancer (10 papers, 2008 to 2025). A tumor composed of atypical neoplastic, often pleomorphic cells that invade other tissues. "Through mitochondrial RNAi screening, SUCLA2 was identified as a key loss-of-nest apoptosis resistance and metastasis driver in human cancers." (PMID 40867281, 2025). "The simultaneous loss of RB1 and SUCLA2 was detected in various cancer types with varied prevalence." (PMID 34359636, 2021). "In addition, as another β-subunit of SUCL, the succinyl-CoA synthase ADP-forming subunit β (SUCLA2) has also been shown to be closely associated with various cancers." (PMID 40867281, 2025). "Currently, there is a lack of further research in the existing literature regarding the potential involvement of SUCLA2 in primary liver malignancies, therefore providing a possible further interesting target in research." (PMID 40830586, 2025). "In this scenario, in sharp contrast to SUCLA2, loss of LATS2 generates certain growth advantages to RB1-deficient cancer." (PMID 34359636, 2021). "Given the critical role of glutaminolysis in many types of cancer progression, the discovery of SUCLA2-coupled regulation of GLS succinylation in precise regulation of glutaminolysis provides GLS succinylation as a novel and promising diagnostic and therapeutic target for cancer care." (PMID 34913133, 2022). "Alterations in SUCLA2 expression led to changes in succinyl-CoA levels and global protein succinylation, regulating different mitochondrial metabolic networks like the TCA cycle flux and contributing to different diseases including cancer." (PMID 40022181, 2025). "Thus, the functions of SUCLA2 and SUCLG2 differ depending on the cancer type." (PMID 37904651, 2023).
mitochondrial disease (4 papers, 2013 to 2020). "The isolation of a mouse ES cell clone with a mutation in Sucla2, a known mitochondrial disease gene, validates the utility of this approach." (PMID 24271779, 2014). "In this study, we test the hypothesis that impairment of SCL activity in patients with mitochondrial disease due to mutations in SUCLA2 leads to increased levels of succinyl-CoA as a donor for succinylation reactions." (PMID 33230181, 2020). "Mutations in SUCLA2 or SUCLG1 cause an incurable, progressive childhood-onset mitochondrial disease characterized by a progressive encephalomyopathy." (PMID 33230181, 2020). "The demonstration of SCS deficiency, mtDNA depletion and elevation of MMA validates the Sucla2 mutant mouse as a model for SUCLA2-dependent mitochondrial disease with mtDNA depletion." (PMID 24271779, 2014). "Also, patients with mitochondrial diseases affecting muscle argue against this (TK2, SUCLA2, SUCLG1, RRM2B, DGUOK, and TYMP)." (PMID 30538797, 2018).
infection (2 papers, 2022 to 2023). The state of being infected such as from the introduction of a foreign agent such as serum, vaccine, antigenic substance or organism. "It is most likely that the infection hampered the tricarboxylic acid (TCA) cycle, because several genes (such as Sdhaf3, Sucla2, Idh3a and Mdh2) encoded the key enzymes in TCA cycle were significantly downregulated." (PMID 36618398, 2022). "Moreover, a decreased expression of enzyme subunits (MDH2 and SUCLA2) and an elevated expression of ACO1 and SUCLG2 in the cycle were observed post infection." (PMID 37256871, 2023).
peripheral neuropathy (1 paper, 2022). A disorder affecting the peripheral nervous system. "In four patients, we identified four disease-causing genes, of which variants in PDHB, MTPAP, and SUCLA2 have been reported not as a cause of CMT but of other diseases associated with symptomatic or subclinical peripheral neuropathy." (PMID 35235001, 2022).
SUCLA2 also shares sentences with these, for which no sentence is quoted: myopathies (2 papers); Ataxia (1); Chorea (1); colon cancer (1); epilepsy (1); epileptic seizures (1); glioblastoma (1); Hematological Disease (1); homocystinuria (1); large intestine cancer (1); Lethal congenital contracture syndrome type 3 (1); neonatal encephalopathy (1); OXPHOS disease (1); primary coenzyme Q10 deficiency (1); propionic acidemia (1); vitamin A deficiency (1); X-linked inherited disorders (1).